ZNF404 (zinc finger protein 404)
Description:
May be involved in transcriptional regulation.
Synonyms: CATED
Tractability: No criterion of Open Targets' tractability assessment is met for any kind of drug.
Gene: Protein-coding gene on chromosome 19 (43,872,365 to 43,901,809, reverse strand). Ensembl gene ENSG00000176222.
Subcellular location: Nucleus
Subcellular location (Human Protein Atlas): Nucleoli; Nucleoli rim; Intermediate filaments
Gene Ontology:
Molecular function: protein binding; DNA-binding transcription factor activity, RNA polymerase II-specific; RNA polymerase II transcription regulatory region sequence-specific DNA binding
Biological process: regulation of transcription by RNA polymerase II; regulation of DNA-templated transcription
Cellular component: nucleolus; nucleus; nuclear lumen
Genetic constraint (gnomAD): Loss-of-function variants: 7 observed, 7.49 expected, observed/expected ratio (o/e) 0.93, 90% interval 0.53 to 1.68. That is too few expected variants to judge how well the gene tolerates losing a copy. Missense variants: 560 observed, 689.94 expected, observed/expected ratio (o/e) 0.81, 90% interval 0.76 to 0.87. Synonymous variants: 191 observed, 220.57 expected, observed/expected ratio (o/e) 0.87, 90% interval 0.77 to 0.98.
Homologues: Orthologues: chimpanzee ZNF404 (95% identical), pig ZNF404 (89% identical), dog ZNF404 (87% identical), Drosophila melanogaster CG3281 (22% identical), Drosophila melanogaster CG2712 (20% identical), Drosophila melanogaster Phs (19% identical). Paralogues in human: ZNF529 (45% identical), ZNF582 (42% identical), ZFP90 (41% identical), ZNF266 (41% identical), ZNF805 (41% identical), ZNF555 (40% identical), ZNF264 (39% identical), ZFP37 (38% identical), ZNF599 (38% identical), ZNF749 (38% identical), ZNF25 (37% identical), ZNF778 (37% identical), and 50 more.
Diseases named in the same sentence as ZNF404 in open-access papers:
ZNF404 is named in the same sentence as 5 diseases in open-access papers, as found by Europe PMC text mining. Sharing a sentence is not in itself a finding about the gene and the disease. The quoted sentences say what the papers report.
breast carcinoma (4 papers, 2013 to 2023). "Mutations in ZNF404 have also been recognized in transcriptional analyses of breast cancer and as a regulating factor in gingival progenitor cells." (PMID 37887305, 2023). "The rs3760982-A allele is associated with an increased risk (odds ratio of 1.06) of breast cancer, thus higher expression of ZNF404 correlates with increased breast cancer risk." (PMID 28957321, 2017). "Therefore, we prioritized SNPs within GWAS loci that are predicted to affect transcription factor binding and module expression of ANKLE1 and ZNF404 to confer breast cancer risk." (PMID 28957321, 2017). "The A/A genotype at rs3760982 is predicted to increase RUNX binding and is correlated with higher expression of ZNF404 in breast cancer tumor samples and breast tissue." (PMID 28957321, 2017).
rosacea (1 paper, 2026). A chronic erythematous skin disorder that affects the face. "Four key genes (ALDH1A1, COL17A1, RELL1, and ZNF404) were identified, with ALDH1A1 as a risk factor and the others as protective factors for rosacea." (PMID 42112773, 2026).
ZNF404 also shares sentences with these, for which no sentence is quoted: tumor (3 papers); cancer (1); ovarian carcinoma (1).